TDG (thymine DNA glycosylase)
Diseases named in the same sentence as TDG in open-access papers (continued):
Sharing a sentence is not in itself a finding about the gene and the disease.
glioma (2 papers, 2022 to 2024). A benign or malignant brain and spinal cord tumor that arises from glial cells (astrocytes, oligodendrocytes, ependymal cells). "In our study, we initially revealed that TDG expression was significantly associated with the prognosis of glioma patients, which was also validated in clinical samples and human glioma cell lines." (PMID 39090080, 2024). "Additionally, simultaneous silencing of TNC reduced or even reversed the glioma promotion caused by TDG overexpression." (PMID 39090080, 2024). "CCK-8 assay revealed that inhibition of TNC remarkably decreased the proliferation of glioma cells when TDG was overexpression." (PMID 39090080, 2024). "The results indicate that high levels of TDG expression in glioma patients is accompanied by a poor prognosis." (PMID 39090080, 2024). "To validate the involvement of TNC in the malignant phenotype of TDG-induced gliomas, we established stable cell lines by transfecting siTNC into TDG-overexpressing cells for the rescue assay." (PMID 39090080, 2024). "Excitingly, tenascin-C (TNC), a crucial ECM glycoprotein involved in the process of cell growth, cell-substrate junction and ECM-receptor interaction, was markedly downregulated in TDG knockdown glioma cells." (PMID 39090080, 2024). "Our research concentrates on the demethylation of TDG in gliomas, demonstrating that upregulation of TDG expression in glioma cells leads to a significant downregulation of TNC methylation levels, thereby promoting TNC expression." (PMID 39090080, 2024). "Subsequently, the glioma cells transfected with TDG knockdown vector and control vector were used to validate the carcinogenic effects of TDG on gliomas in vivo and in vitro, respectively." (PMID 39090080, 2024). "As the main participant of DNA active demethylation, the expression of TDG in glioma is positively correlated with TNC." (PMID 39090080, 2024). "Based on our findings, we conclude that TDG exerts an indispensable role in TNC active DNA demethylation in gliomas." (PMID 39090080, 2024). "A total of 783 differential genes were detected following the knockdown of TDG in glioma cells, and principal components analysis was conducted." (PMID 39090080, 2024). "We delved further into understanding how TDG-mediated active DNA methylation influences TNC gene expression and explore TNC association with tumor tumourigenesis and immune microenvironment in glioma." (PMID 39090080, 2024). "To elaborate on the potential oncogenic function of TDG in gliomas, we screened high- and low-expressing glioma tissues for differentially expressed genes (DEGs) and enriched for GO and KEGG pathways using TCGA mRNA sequencing data." (PMID 39090080, 2024). "Gliomas are characterized by a high degree of vascularization, TDG regulates TNC expression through active demethylation and we have identified the demethylation sites to fully elucidate this process." (PMID 39090080, 2024). "Wound-healing and transwell assays verified that silencing TDG appeared to inhibit glioma cell migration and invasion." (PMID 39090080, 2024). "In summary, the present evidence reveals that TDG silencing inhibits glioma proliferation, migration, invasion and cell cycle progression in vitro." (PMID 39090080, 2024). "This research indicates TDG expression is overexpressed in gliomas and correlated with poor prognosis." (PMID 39090080, 2024). "As a result, the role of TDG in epigenetic regulation to facilitate glioma development extends knowledge into the mechanisms of TDG-mediated demethylation regulation and translates into therapeutic strategies for GBM." (PMID 39090080, 2024). "We found that TDG has the same expression characteristics at the protein level in glioma tissues." (PMID 39090080, 2024).
glioma (continued). "To verify that the downregulation of methylation levels of TNC in gliomas is mediated by active DNA demethylation of TDG, we confirmed by ChIP- qPCR assay that TDG was able to combine with the chr9: 117826025 position of TNC, participate in the DNA demethylation process of TNC." (PMID 39090080, 2024). "TDG knockdown suppressed the malignant phenotype of gliomas both in vitro and vivo." (PMID 39090080, 2024). "Given the heterogeneity of different grades of gliomas, we compared the expression levels of TDG in different grades gliomas and observed higher TDG expression levels in high-grade gliomas, the expression level of TDG was upregulated and positively correlated with the tumor grade." (PMID 39090080, 2024). "The CKK8 assay revealed that silencing TDG severely inhibited the proliferation of glioma cells." (PMID 39090080, 2024). "In the following, to prove the impact of TDG on the regulation of glioma growth in vivo." (PMID 39090080, 2024). "Simultaneously, whether the active DNA demethylation mediated by TDG can interact with DNA methylase may collectively influence the occurrence of glioma." (PMID 39090080, 2024). "However, the specific mechanisms of TDG-mediated active DNA demethylation in gliomas remain unclear." (PMID 39090080, 2024). "Therefore, the focus of further research will be to determine whether TDG can directly or indirectly mediate the formation of glioma neovascularisation and whether it can also mediate the expression of TNC." (PMID 39090080, 2024). "Meanwhile, we further delved into the specific mechanisms of TDG-mediated active DNA demethylation leading to the overexpression of TNC and promoting glioma tumourigenesis by RNA-seq, ChIP-qPCR, and MeDIP-qPCR." (PMID 39090080, 2024). "Our findings strongly implicate that TDG exerts a function similar to tumor-promoting factors, mediating the up-regulation of TNC expression, and is involved in glioma progression." (PMID 39090080, 2024). "Using a series of clinical glioma specimens, we investigated the TDG protein expression levels in 5 LGG, 5 GBM and 5 normal brain tissues by IHC, as well as mRNA expression levels of TDG in the SVGP12 and U251 cell lines by qPCR." (PMID 39090080, 2024). "In this study, we first explored the distinct expression of TDG in glioma tissues as opposed to normal tissues and pro-oncogenic function." (PMID 39090080, 2024). "Collectively, TDG is involved in the induction of TNC hypomethylation in GBM, which elevates TNC expression and significantly promotes the malignant phenotype of human glioma cells." (PMID 39090080, 2024). "Subsequently, we performed MeDIP analysis with TDG knockdown and control U251 cells, as well as checked the alterations in TNC expression using RT-qPCR and protein blotting, indicating that TDG knockdown greatly enhanced the DNA methylation level of TNC, suppressing TNC expression in glioma cells." (PMID 39090080, 2024). "TDG expression levels were elevated in glioma tissues versus normal brain tissues." (PMID 39090080, 2024).
non-small cell lung carcinoma (2 papers, 2021). A group of at least three distinct histological types of lung cancer, including non-small cell squamous cell carcinoma, adenocarcinoma, and large cell carcinoma. "LINC00467 has been reported to be transcriptionally induced by STAT1 in lung adenocarcinoma cells; additionally, LINC00467 was up-regulated by TDG-mediated acetylation in non-small cell lung cancer." (PMID 33996559, 2021).
acute myeloid leukemia (1 paper, 2022). Acute myeloid leukemia (AML) is a group of neoplasms arising from precursor cells committed to the myeloid cell-line differentiation. "In acute myeloid leukemia, TDG interacts with DNMT3A to reduce its methylation ability." (PMID 35414793, 2022).
adenoma (1 paper, 2017). A neoplasm arising from the epithelium. "Since TDG is a known co-activator of estrogen receptor (ER) α and β, and ovariectomy increases adenoma formation in ApcMin mice, it is possible that the known protective effect of female hormones, and especially estrogens, on CRC formation is TDG-dependent." (PMID 29163805, 2017).
atherosclerosis (1 paper, 2018). A disease characterized by the build-up of fatty material and calcium deposition in the arterial wall resulting in partial or complete occlusion of the arterial lumen. "However, SIRT1 also activates other components of the BER pathway, including the enzymes thymine DNA glycosylase, apurinic/apyrimidinic endonuclease 1, and poly(ADP-ribose) polymerase 1,48,49 which may partly explain the profound effect of VSMC SIRT1 knockout in atherosclerosis." (PMID 29643057, 2018).
B-cell chronic lymphocytic leukemia (1 paper, 2017). "All three genes specific to the M3 subtype (ATXN3, thymine-DNA glycosylase (TDG, 12q24.1), and HCLS) also showed possible associations with cancer risks, such as B-cell chronic lymphocytic leukemia (B-CLL)." (PMID 28249600, 2017).
brain tumour (1 paper, 2017). "To get an insight into potential molecular mechanisms for the 5caC enrichment in medulloblastoma and ependymoma cells, we examined the levels of TET1/2/3 and TDG transcripts in the four paediatric brain tumour cell lines and HeLa cells." (PMID 28228863, 2017).
C. perfringens infection (1 paper, 2020). "In comparison with uninfected turkeys, C. perfringens infection increased 8-OHdG levels and decreased the activity of APE-1, TDG and ANPG in the wall of the ileum (P < 0.001)." (PMID 32264939, 2020). "Similarly to Experiment 1, C. perfringens infection increased 8-OHdG levels and decreased the activity of APE-1, TDG and ANPG in the wall of the ileum (P < 0.001)." (PMID 32264939, 2020).
cervical cancer (1 paper, 2022). A primary or metastatic malignant neoplasm involving the cervix. "Studies have shown that the expression of PCNA in cervical tissues increases with the increase in CIN and cervical cancer grade.TDG plays an important role in DNA demethylation." (PMID 35379200, 2022). "But few studies have examined TDG in CIN and cervical cancer, so its role in the progression of CIN requires further analysis." (PMID 35379200, 2022). "In this experiment, we found that TDG and LIG1 were expressed at high levels in cervical cancer, and OGG1 expression was low in cervical cancer (P < 0.05)." (PMID 35379200, 2022). "The expression levels of PCNA, TDG, and LIG1 were elevated in cervical cancer group compared with the normal and CIN groups (P < 0.05)." (PMID 35379200, 2022). "Few studies have examined LIG1, SMUG1, and TDG in CIN and cervical cancer." (PMID 35379200, 2022). "However, expression levels of TDG, LIG1 and OGG1 have not been examined in cervical cancer tissues." (PMID 35379200, 2022).
cervical intraepithelial neoplasia (1 paper, 2022). "At the same time, the early warning model including ABCG2 + PCNA+TDG genes provided a new idea and target for clinical prediction and blocking the evolution of cervical intraepithelial neoplasia malignant transformation from the aspect of cervical microbiological related genes." (PMID 35379200, 2022).
cervical squamous cell carcinoma (1 paper, 2023). A squamous cell carcinoma arising from the cervical epithelium. "The results showed that compared with the control group of cervical squamous cell carcinoma SiHa cells, the expression of differential proteins PCNA, ATM, LIG1 and HMGB1 in Ect1/E6E7 cells decreased significantly, while the expression of TDG and OGG1 proteins increased significantly." (PMID 36726132, 2023).
colon adenocarcinoma (1 paper, 2017). "Examination of the TCGA COAD (colon adenocarcinoma) and READ (rectal adenocarcinoma) data sets also revealed a wide range of TDG mRNA expression ratios between normal and tumor pairs in matched samples." (PMID 29163805, 2017).
colon cancer (1 paper, 2022). "The Transwell assay data showed that the overexpression of DNMT3A partially reversed the decrease in the migration and invasion abilities of colon cancer cells that had been induced by TDG overexpression." (PMID 35414793, 2022). "To verify that TDG inhibits the migration and invasion of colon cancer cells through the DNMT3A-TIMP2 axis, we performed a rescue experiment." (PMID 35414793, 2022). "DNMT3A overexpression partially rescued the TDG-induced decrease in the migration and invasion abilities of colon cancer cells, and rescued the TDG-induced increase in the TIMP2 expression." (PMID 35414793, 2022). "There were metastatic sites in the lungs of the nude mice in the HCT116-Lv-Ctrl group, but no metastases were observed in the HCT116-Lv-TDG group; that is, TDG overexpression inhibited the metastasis of human colon cancer cells in vivo." (PMID 35414793, 2022). "Therefore, we propose that TDG can inhibit the migration and invasion abilities of colon cancer cells by reducing their level of DNMT3A, decreasing the TIMP2 promoter methylation, and increasing the expression of TIMP2." (PMID 35414793, 2022). "We further examined the TDG expression in the CRC tissues and in human colon cancer cells." (PMID 35414793, 2022). "In summary, TDG interacts with DNMT3A to promote ubiquitination degradation, induces the hypomethylation of the TIMP2 promoter, increases TIMP2 expression, and significantly inhibits the migration and invasion abilities of human colon cancer cells." (PMID 35414793, 2022). "Furthermore, the ChIP, MSP, and rescue experiments results confirmed that TDG accelerated the degradation of DNMT3A and significantly regulated the transcription and expression of TIMP2, thereby affecting the migration and invasion of human colon cancer cells." (PMID 35414793, 2022).
ependymoma (1 paper, 2017). A WHO grade II, slow growing tumor of children and young adults, usually located intraventricularly. "In the present study, we aimed to determine the global levels and nuclear distribution of oxi-mCs as well as the expression of TET1/2/3 and TDG transcripts in tumour cell lines derived from paediatric medulloblastomas and ependymomas." (PMID 28228863, 2017).
germ cell cancers (1 paper, 2013). "A meta-analysis of gene expression data of germ cell cancer tissues and corresponding cell lines demonstrates high expression of TET1 and the DNA glycosylase TDG, suggesting that germ cell cancers utilize the oxidation pathway for active DNA demethylation." (PMID 24386123, 2013).
hepatocellular carcinoma (1 paper, 2021). A malignant tumor that arises from hepatocytes. "Furthermore, the deletion of thymine DNA glycosylase (TDG), a base excision repair enzyme that plays an essential role in the maintenance of epigenetic stability in cells, 8 weeks post-partum promoted hepatocellular carcinoma and dysregulation of BA homeostasis." (PMID 33573273, 2021).
Histiocytosis (1 paper, 2019). An excessive number of histiocytes (tissue macrophages). "The significance of these histopathological findings and their relationship to TDG inactivation are unclear, because histiocytosis has been reported to be associated with oral gavage." (PMID 30674989, 2019).
Hyperglycemia (1 paper, 2023). An increased concentration of glucose in the blood. "AKG treatment in hyperglycemia-exposed H9c2 cells also showed a similar reversal of global 5mC and 5hmC deposition, possibly by improving TDG function and its association with TET1 to complete the DNA demethylation cycle." (PMID 37101286, 2023).
intestinal tumor (1 paper, 2017). "On the other hand, TDG DNA repair activity may also play a role in intestinal tumor formation, via maintenance of genomic stability of CpG sites, i.e. the subset of tumors with low TDG expression may exhibit high levels of transition mutations at CpG sites." (PMID 29163805, 2017). "In this article, we conducted human and mouse studies, which concordantly establish a role for inactivation of TDG, as an important tumor suppressor in the pathogenesis of a subset of intestinal tumors." (PMID 29163805, 2017). "To study the role of TDG in intestinal tumor formation, we conditionally inactivated Tdg in the small intestine and colon." (PMID 29163805, 2017). "Both mutant Tdg x ApcMin mice and the low TDG/low APC patient subset are characterized by an excess of female cases, which indicates that TDG may normally mediate the protective effects of estrogen on intestinal tumor formation." (PMID 29163805, 2017).
nasopharyngeal carcinoma (1 paper, 2010). A carcinoma arising from the nasopharyngeal epithelium. "Mir-29c was reported to be under expressed in nasopharyngeal carcinomas and up regulated genes COL4A1, COL4A2 and TDG." (PMID 21114830, 2010).
renal clear cell carcinoma (1 paper, 2020). "For example, in renal clear cell carcinoma, the expressions of TET1, TET3, and TDG are positively correlated with that of hsa-miR-21-5p." (PMID 32637580, 2020). "For renal clear cell carcinoma samples, gene set enrichment analysis (GSEA) Kyoto Encyclopedia of Genes and Genomes (KEGG) pathway enrichment showed a positive correlation between expressions of TET3/TDG and miRNAs in cancer." (PMID 32637580, 2020).
Rett syndrome (1 paper, 2018). A severe neurodevelopmental disorder affecting the central nervous system.